HIC1 (HIC ZBTB transcriptional repressor 1)
Diseases named in the same sentence as HIC1 in open-access papers (continued):
Sharing a sentence is not in itself a finding about the gene and the disease.
osteosarcoma (3 papers, 2011). A usually aggressive malignant bone-forming mesenchymal neoplasm, predominantly affecting adolescents and young adults. "Hypermethylated in cancer 1 (Hic1), by its name, is another epigenetically modified locus that has also been reported to have a tumor suppressor function in osteosarcoma." (PMID 21403899, 2011). "In addition, it has been found that 17% of pediatric osteosarcomas display hypermethylation of the HIC1 promoter." (PMID 21253504, 2011).
prostate adenocarcinoma (3 papers, 2020 to 2023). "RT-qPCR analyses on a cohort of 30 prostate tumor samples of different grades demonstrated that high HIC1 expression is found in stroma-rich prostate adenocarcinoma." (PMID 33227080, 2020).
uveal melanoma (3 papers, 2017 to 2023). A melanoma derived from melanocytes of the uveal tract. "For instance, it has been reported that HIC1 prohibited the progression of uveal melanoma by activating lncRNA-numb, providing a potential therapeutic target for uveal melanoma." (PMID 37388742, 2023). "For example, hypermethylated in cancer 1 (HIC1) can induce uveal melanoma progression by activating lncRNA-numb." (PMID 29244840, 2017). "Hypermethylated in cancer 1 (HIC1) regulates lncRNA NUMB in uveal melanoma." (PMID 34439196, 2021).
breast tumor (2 papers, 2006 to 2018). "Our data suggests that HIC-1 regulated by miR-4532 is one of the important factors that promotes drug resistance in breast tumor, which also has been demonstrated in the clinical samples and the database of public microarray datasets." (PMID 30202238, 2018). "Methylation of RASSF1A, RARβ2 and HIC-1 gene promoters were studied in healthy donors and patients with breast tumours." (PMID 16641902, 2006). "In the present study we investigated the methylation of HIC-1, RASSF1A and RARβ2 genes promoters in cirDNA derived from plasma and cell-surface-bound fractions of patients with breast tumours." (PMID 16641902, 2006).
chronic prostatitis (2 papers, 2015 to 2019). An infectious or non-infectious chronic inflammatory process that affects the prostate gland. "In agreement with this, dense hypermethylation of one of the HIC1 alleles has earlier been reported in a number of normal human tissues, including kidney, and histologically normal and benign hyperplastic prostate tissues." (PMID 26170120, 2015). "Hic1, Zfp148, and Mfge8 gene mutations were detected in chronic prostatitis somatic cells." (PMID 31088536, 2019).
cleft palate (2 papers, 2010 to 2017). Cleft palate is a fissure type embryopathy that affects the soft and hard palate to varying degrees. "HIC1 was also strongly associated with cleft palate in a genome-wide association study of humans." (PMID 28806925, 2017).
hyperglycaemia (2 papers, 2019 to 2024). "However, the underlying mechanism that HIC1 regulates hyperglycaemia‐mediated EndMT in metabolic memory and DKD lacks exploration." (PMID 38686489, 2024). "This study demonstrated that the hyperglycaemia‐mediated interaction between Sirt7 and HIC1 exerts a role in the metabolic memory in DKD by inactivating SDC1 transcription and mediating EndMT despite glucose normalization in HGECs." (PMID 38686489, 2024). "In another study, hyperglycemia altered the expression of hypermethylated in cancer 1 (HIC1) and increased ROS accumulation in renal tubular epithelial cells (HK-2) by epigenetically repressing SIRT1." (PMID 31546918, 2019). "To encapsulate, our findings suggest that hyperglycaemia triggers a mutual regulation between Sirt7 and HIC1 that persists even after glucose levels normalize, thereby establishing a positive feedback loop that contributes to the development of metabolic memory." (PMID 38686489, 2024). "Our data indicated a downregulation of hyperglycaemia‐induced αSMA by Sirt7 overexpression supplemented with glucose normalization, which increased the hyperglycaemia‐mediated reduction of HIC1, SDC1 and CD31 expression in the kidneys of the rats, while insulin alone did not work." (PMID 38686489, 2024).
laryngeal carcinoma (2 papers, 2021 to 2024). Carcinoma that arises from the laryngeal epithelium. "Genetic susceptibility plays a role as well, with certain genetic polymorphisms, such as those in the DIAPH2, PTPRD, and HIC1 genes, being associated with an increased risk of laryngeal cancer." (PMID 38835555, 2024). "The aim of our study was to determine the relationship between genetic variations DIAPH2 (rs6620138), PTPRD (rs3765142) and HIC1 (rs9901806) and laryngeal cancer risk in 267 patients with histologically confirmed laryngeal cancer and 157 controls." (PMID 34299935, 2021). "This study was designed to assess the association between DIAPH2, PTPRD and HIC1 SNPs and laryngeal cancer risk." (PMID 34299935, 2021). "The relationship between the genetic variation of DIAPH2, PTPRD and HIC1 genes and the genetic susceptibility to laryngeal cancer was investigated in this study for the first time." (PMID 34299935, 2021). "Statistical analysis to calculate the relationship between DIAPH2, PTPRD and HIC1 genes polymorphism and pathogenesis of laryngeal cancer." (PMID 34299935, 2021). "We show a significant difference in the allele’s distribution of DIAPH2 and HIC1 between the study subgroup patients with laryngeal cancer and control subgroups." (PMID 34299935, 2021). "The relationship between genetic variations DIAPH2 (rs6620138), PTPRD (rs3765142) and HIC1 (rs9901806) and the onset of laryngeal cancer were investigated." (PMID 34299935, 2021). "The aim of our study was to try to find a link between the studied polymorphisms of the DIAPH2, HIC1 and PTPRD genes and the risk of laryngeal cancer development." (PMID 34299935, 2021). "We hypothesized that if we showed a difference in the distribution of the polymorphisms of the DIAPH2, HIC1 and PTPRD genes studied, this would indicate a significant effect of these genetic variations on the risk of developing laryngeal cancer." (PMID 34299935, 2021). "Consequently, however, we found only a significant difference in the distribution of rs6620138 DIAPH2 between subgroups smokers and nonsmokers in the case group, HIC1 and PTPRD genotypes and alleles between the study subgroup patients with laryngeal cancer." (PMID 34299935, 2021).
leukaemia (2 papers, 2015 to 2016). "Recently, our and other studies have indicated that HIC1 is frequently hypermethylated in a variety of solid tumors and leukemia, However, the consequences of epigenetic modification on HIC1 promoter in NSCLC remain unclear." (PMID 27107418, 2016).
melanoma (2 papers, 2023 to 2025). A malignant, usually aggressive tumor composed of atypical, neoplastic melanocytes. "Several studies have explored the clinical significance and functions of HIC1 in metastatic urothelial cancer and melanoma." (PMID 37388742, 2023). "In vivo studies revealed that ART directly targeted Ido1 in B16F10 cells, decreased Hic1 levels, promoted Hmox1 transcription, facilitated ROS production and lipid peroxidation, aa and induced ferroptosis in melanoma cells, leading to cell proliferation inhibition in melanoma." (PMID 41160271, 2025).
myelodysplastic syndrome (2 papers, 2006 to 2025). A clonal hematopoietic disorder characterized by dysplasia and ineffective hematopoiesis in one or more of the hematopoietic cell lines. "As a unique cytosine analog, decitabine was initially recognized as a therapeutic agent for hematologic malignancies, including myelodysplastic syndromes (MDS) and CML, where it reactivates anti-tumor genes like p15INK4b, HIC1, p21CIP1, and p57KIP2 and upregulates CTAs like SPAN-Xb." (PMID 41194129, 2025).
ovarian tumors (2 papers, 2010 to 2020). "CGIs associated with three putative tumor suppressor genes APC, HIC1 and RASSF1 have previously been shown to be frequently hyper-methylated in breast and ovarian tumors when compared to healthy tissue." (PMID 20544021, 2010).
papillary thyroid carcinomas (2 papers, 2016 to 2018). "Thus, HIC1 methylation frequency and HIC1 mRNA and protein expression in papillary thyroid carcinoma, is closely associated with prognosis." (PMID 27793057, 2016). "HIC1 protein expression in the papillary thyroid carcinomas (0.42 ± 0.07) was lower than in the adjacent normal tissues (0.94 ± 0.11; p < 0.01) and the inverse was true for SIRT1 protein expression." (PMID 27793057, 2016). "In papillary thyroid carcinoma, it is likely that reduced expression of the HIC1 gene contributes to upregulation of SIRT1 expression." (PMID 27793057, 2016). "In the papillary thyroid carcinoma tissues, HIC1 expression was relatively low compared to the paired normal thyroid tissue and only expressed in the nucleus." (PMID 27793057, 2016). "Consistent with increased methylation, the levels of HIC1 mRNA and protein expression in papillary thyroid carcinomas were significantly lower than in adjacent normal tissues." (PMID 27793057, 2016). "The relative HIC1 mRNA expression was significantly lower in papillary thyroid carcinomas (0.47 ± 0.07) than in the paired normal thyroid tissues (2.12 ± 0.10)." (PMID 27793057, 2016). "Aberrant expression of HIC1/SIRT1 and hypermethylation of the HIC1 promoter may be critical for the development and progression of papillary thyroid cancer." (PMID 27793057, 2016). "Hypermethylation of the HIC1 promoter and aberrant expression of HIC/SIRT1 may be useful for assessing the risk of developing thyroid papillary carcinoma and may be a novel therapeutic target." (PMID 27793057, 2016). "However, the importance of HIC1 expression in the development of papillary thyroid carcinoma, especially in Chinese patients, is uncertain." (PMID 27793057, 2016). "In summary, hypermethylation of the HIC1 promoter in thyroid papillary carcinoma might contribute to aberrant expression of HIC1/SIRT1, which in turn promotes thyroid cancer." (PMID 27793057, 2016). "We hypothesized that HIC1 promoter methylation would cause abnormal expression of HIC1/SIRT1, thereby enhancing the development and progression of papillary thyroid carcinoma." (PMID 27793057, 2016). "Wu et al36 verified that restoration of HIC1 expression via 5‐Aza treatment reduced SIRT1 expression and cell propagation, and led to senescence, cell cycle arrest and apoptosis in thyroid papillary carcinoma." (PMID 30039914, 2018). "The negative correlation between HIC1 methylation and the expression of HIC1 mRNA and protein suggested that hypermethylation of the HIC1 promoter inhibited HIC1 expression, and may be associated with the development of papillary thyroid carcinoma." (PMID 27793057, 2016). "Therefore, we assessed the level of methylation in the HIC1 promoter and the mRNA and protein expression levels of HIC1 and SIRT1 in human thyroid papillary carcinoma and tumor adjacent control tissues." (PMID 27793057, 2016). "The significantly higher levels of HIC1 methylation in papillary thyroid carcinomas compared to normal tissues suggests that excessive methylation is occurring in papillary thyroid carcinomas." (PMID 27793057, 2016). "Within the papillary carcinoma samples, there were also negative correlations between the amount of HIC1 methylation and HIC1 mRNA expression (p < 0.05), and between HIC1 methylation and HIC1 protein expression (p < 0.05)." (PMID 27793057, 2016). "In papillary thyroid carcinoma, the methylation and expression patterns of HIC1 have not yet been described and it is unclear whether the HIC1/SIRT1 pathway is involved in the development and progression of disease." (PMID 27793057, 2016). "Consistent with the mRNA results, there was also a negative correlation between HIC1 and SIRT1 protein expression in the papillary thyroid carcinomas (p < 0.05)." (PMID 27793057, 2016). "A negative correlation between the mRNA expression levels of HIC1 and SIRT1 was observed in the papillary thyroid carcinomas." (PMID 27793057, 2016).
parathyroid tumors (2 papers, 2018 to 2021). "We further investigated genes that are rarely studied in parathyroid tumors, such as HIC1, which is a tumor suppressor gene (17p13.3) that is frequently deleted or epigenetically silenced by DNA methylation." (PMID 33778063, 2021). "Overexpression of HIC1 leads to a decrease in the clonogenic survival of parathyroid tumor cells, strongly supporting a regulatory role for HIC1 in the growth of parathyroid glands." (PMID 33778063, 2021). "HIC1 was generally underexpressed, regardless of the hyperparathyroidism, including multiple parathyroid tumors in the same patient." (PMID 33778063, 2021).
phaeochromocytomas (2 papers, 2023 to 2025). "The epigenetic analysis revealed consistent methylation of HIC1 and CASP8 in pheochromocytomas, which was significantly more frequent in VHL pheochromocytomas compared to sporadic cases, underlying the presence of differing pathophysiological mechanisms between the two types of tumors." (PMID 40558831, 2025). "With regards to DSS Kaplan–Meier curves, we found that HIC1 expression was significantly connected with poor DSS in ACC (P = 0.011), KIRP (P = 0.003), and UVM (P < 0.001), while was related to better DSS in pheochromocytoma and paraganglioma (PCPG) (P = 0.004) and UCEC (P = 0.002)." (PMID 37388742, 2023).
sarcoma (2 papers, 2019 to 2023). A usually aggressive malignant neoplasm of the soft tissue or bone. "In addition, HIC1 (hypermethylated in cancer 1) promoter DNA hypermethylation is an early event in several cancers such as epithelial cancers in males and lymphomas and sarcomas in females." (PMID 30813436, 2019).
seminoma (2 papers, 2020 to 2022). A radiosensitive malignant germ cell tumor found in the testis (especially undescended), and extragonadal sites (anterior mediastinum and pineal gland). "Seminomas are known to show selective hypermethylation at several tumor suppressors, such as MGMT, SCGB3A1, RASSF1A, HIC1, and PRSS21." (PMID 32176716, 2020). "Promoter hypermethylation of the RASSF1A and HIC1 genes was observed in resistant non-seminomas, while sensitive non-seminomas showed hypermethylation of MGMT and RARB." (PMID 35625709, 2022).
thyroid cancer (2 papers, 2016 to 2023). "Tissue analyses confirmed that the level of HIC1 expression in thyroid carcinoma tissue was greater than in normal tissue, and that within thyroid carcinomas there was a negative correlation between HIC1 and SIRT1 expression." (PMID 27793057, 2016). "HIC1 gene measurements in thyroid cancer and adjacent normal tissues were performed." (PMID 27793057, 2016). "The level of HIC1 methylation was also higher in thyroid carcinoma tissues than adjacent tissues." (PMID 27793057, 2016). "Significant differences were observed in the levels of HIC1 and SIRT1 protein expression by Western blot analysis in the thyroid cancer tissues and adjacent normal tissues." (PMID 27793057, 2016). "The mRNA expression levels of HIC1 and SIRT1 were measured in samples from thyroid carcinomas and adjacent normal thyroid tissues." (PMID 27793057, 2016).
asthma (1 paper, 2021). "We identified SLC7A11, SLC2A12, ZEB1, ATF3, and HIC1 common between DEGs and TFs involved with asthma and ferroptosis." (PMID 34257337, 2021).
Beckwith-Wiedemann syndrome (1 paper, 2018). Beckwith-Wiedemann syndrome (BWS) is a genetic disorder characterized by overgrowth, tumor predisposition and congenital malformations. "Opposite hIC1 methylation and imprinting defects are associated with the Beckwith-Wiedemann syndrome (BWS, MIM #130650) and the Silver Russell syndrome (SRS, MIM #180860), two IDs characterised by congenital overgrowth and congenital undergrowth, respectively." (PMID 29470501, 2018).
bladder urothelial carcinoma (1 paper, 2011). "In the human bladder urothelial carcinoma samples examined, increased HIC1 promoter methylation was detected in 100% (30/30) of the samples and reduced expression was observed in 70.0% of the 30 tumor samples." (PMID 22140553, 2011). "Hypermethylated in cancer 1 (HIC1) and slit homolog 2 (SLIT2) were identified as having differentially up-regulated methylation status of their promoter regions and dramatically down-regulated expression level across all the bladder urothelial carcinoma tissue samples." (PMID 22140553, 2011).
bone tumors (1 paper, 2012). "HIC1 might play a role of bone tumor progression and metastasis." (PMID 23199169, 2012). "High-level amplification of TGFβ2 (1q41), CCND3 (6p21), WI-6509 (11qtel), SHGC-5557 (12ptel), TCL1A (14q32.1), CREBBP (16q13.3), HIC1 (17p13.3), THRA (17q11.2), AFM217YD10 (17qtel), LAMA3 (18q11.2), RUNX1 (21q22.3) and D22S543 (22q11), was commonly observed in aggressive bone tumors." (PMID 23199169, 2012).
chordoma (1 paper, 2013). Chordomas are rare malignant tumors arising from embryonic remnants of the notochord in axial skeleton. "HIC1 methylation could be used as a target for pharmacologic DNA-methyltransferase and could therefore suit as a potential new target to treat chordoma patients." (PMID 23533570, 2013). "By comparing methylation patterns of blood from healthy individuals and chordoma patients we found 20 significantly differentially methylated genes; 15 hypermethylated in chordoma (for example RASSF1, KL, RARB, HIC1, and FMR1) and 5 hypomethylated (HSD17B4, BAZIA, STAT1, NEUROGL, and JUP)." (PMID 23533570, 2013).
colorectal tumor (1 paper, 2021). "Next, we examined whether HIC1 was implicated in FBXW11-mediated colorectal tumor growth." (PMID 34642302, 2021). "Subsequently, the effect of FBXW11 on the ubiquitination level of HIC1 in colorectal tumor cells was examined." (PMID 34642302, 2021). "The involvement of HIC1 and SIRT1 during FBXW11-mediated colorectal tumor growth was also explored." (PMID 34642302, 2021).
ependymoma (1 paper, 2022). A WHO grade II, slow growing tumor of children and young adults, usually located intraventricularly. "The methylation of RASSF1A, HIC1 and CDKN2A are the most common epigenetic changes demonstrated in ependymomas." (PMID 34854470, 2022).
epilepsy (1 paper, 2022). A brain disorder characterized by episodes of abnormally increased neuronal discharge resulting in transient episodes of sensory or motor neurological dysfunction, or psychic dysfunction. "Of the 30 protein coding genes with identified coding sequence or expression differences, ten had a prior association with seizure or epilepsy based on literature and database searches, including Aspa, Hic1, Nlrp1a, Nlrp1b, Pafah1b1, Smg6, Trpv1, Trpv3, Ywhae and 6330403K07Rik." (PMID 35606653, 2022).
esophageal squamous cell carcinoma (1 paper, 2015). Esophageal squamous cell carcinoma (ESCC) is a type of esophageal carcinoma (EC) that can affect any part of the esophagus, but is usually located in the upper or middle third. "In this study, we investigated a role of HIC1 in esophageal squamous cell carcinoma (ESCC) and the underlying mechanisms." (PMID 26510908, 2015). "The expression and the methylation status of HIC1 were detected by real-time RT-PCR and MSP in human esophageal squamous cell carcinoma cell lines." (PMID 26510908, 2015).